MIR3138 (microRNA 3138)
Synonyms: hsa-mir-3138; mir-3138
Gene: MicroRNA gene on chromosome 4 (10,078,611 to 10,078,692, reverse strand). Ensembl gene ENSG00000264931.
Homologues: Orthologues: chimpanzee MIR3138 (100% identical).